CXCR4 (C-X-C motif chemokine receptor 4)
Diseases named in the same sentence as CXCR4 in open-access papers (continued):
Sharing a sentence is not in itself a finding about the gene and the disease.
leukemia (continued). "Indeed, direct leukemia-MSC contact via VCAM-1/VLA-4 interactions, together with CXCL12/CXCR4 signaling and inflammatory cytokine signaling, may contribute, to a different extent, based on space and time, to enhance leukemia survival by activating NF-kB signaling within the leukemic BM niche." (PMID 33922612, 2021). "Our group showed that the potent peptidic CXCR4 inhibitor, LY2510924, had anti-leukemia efficacy as a single agent and was strongly synergistic with chemotherapy in vivo." (PMID 32629802, 2020). "Efficient and durable CXCR4 blockade by LY2510924 induced physical mobilization and differentiation of leukemic cells, translating into enhanced anti-leukemia efficacy." (PMID 32629802, 2020). "AMD3465 is also a selective small-molecule CXCR4 antagonist that antagonizes CXCL12 stimulation of chemotaxis and prosurvival signaling pathways in leukemia cells." (PMID 33363463, 2020). "Several small molecules, peptides, and antibodies targeting the CXCR4 axis, such as plerixafor, BL-8040/BKT140, LY2510924, PF-06747143, BMS-936564, and NOX-A12, have shown promising results in leukemia, lymphoma, and myeloma." (PMID 32260318, 2020). "One example of an optimized EPI-X4 derivative is WSC02 that encompasses only 12 residues and inhibits CXCR4-tropic HIV-1 infection and suppresses leukemia cell migration towards CXCL12 with IC50 values in the nanomolar range." (PMID 32994431, 2020). "CXCR4, expressed on the surface of hematopoietic stem cells and leukemia blast cells, is activated by CXCL12, and it participates in leukemia cell proliferation and infiltration, as well as in conferring resistance to chemotherapy drugs." (PMID 33381455, 2020). "In NOD/SCID mice, CXCR4 inhibitor AMD3465 in combination with G-CSF and protein kinase inhibitor sorafenib improved survival and resulted in reduction of leukemia cells in bone marrow and their absence in spleen or liver." (PMID 32754595, 2020). "C-X-C chemokine receptor type 4 (CXCR4) and its ligand, C-X-C motif chemokine 12 (CXCL12), are key mediators of leukemia/stroma interaction." (PMID 32629802, 2020). "CXCR4 inhibition (with CXCR4 antagonist AMD‐3100) impaired grafting of ALL cells to bone marrow, leukemia development and CNS infiltration." (PMID 32194848, 2020). "C-X-C chemokine receptor type 4 (CXCR4) is involved in several intractable disease processes, including HIV infection, cancer cell metastasis, leukemia cell progression, rheumatoid arthritis, asthma and pulmonary fibrosis." (PMID 32994431, 2020). "Based on these data, FLT3-ITD facilitates the interaction between leukemia cells and the microenvironment by enhancing CXCL12/CXCR4 signaling." (PMID 31434952, 2019). "CXCR4 inhibition (with CXCR4 antagonist AMD-3100) impaired grafting of T-ALL cells to bone marrow, leukemia development and CNS infiltration." (PMID 31481958, 2019). "In functional assays, CD26 disrupted the SDF-1α-CXCR4 axis by cleaving SDF-1α and facilitated leukemia escape from the BM niche." (PMID 29466292, 2018). "Here, [68Ga]Pentixafor PET enabled visualization of CXCR4-positive leukemic burden, and CXCR4-directed ERT with [177Lu]Pentixather resulted in the efficient reduction of leukemia in leukemia-harboring tissues (spleen, bone marrow)." (PMID 30105558, 2018). "Blocking CXC-chemokine receptor type 4 (CXCR4), which binds to SDF-1, is known to dislodge leukemia stem cells (LSCs) from the BM stroma, which then become susceptible to chemotherapy." (PMID 31069313, 2018). "We also show that CXCR4 surface expression is central to the migratory ability of CD4+CD8+ cells and such an expression is regulated by Notch3 through β-arrestin in human leukemia cells." (PMID 30038265, 2018). "SDF-1α, the protein product of CXCL12, controls the trafficking of hematopoietic stem cells (HSC) and leukemia stem cells (LSC) from and to the BM cavity through the binding to CXCR4." (PMID 29137349, 2017).
leukemia (continued). "We next tested the efficacy of PF-06747143 in leukemia development in PDX model reconstituted with P17 patient cells, characterized by low CXCR4 expression (P17CXCR4-low)." (PMID 28779088, 2017). "Nevertheless, it has been shown, in an experimentally-induced leukemia model, that HSC increased CXCR4 expression, showing the similarity to our in vitro model." (PMID 28216566, 2017). "In summary, the robust single agent efficacy demonstrated in both CXCR4 low and high PDX preclinical models suggests the potential of PF-06747143 as a new agent for leukemia treatment, including relapsed refractory and unfit patients." (PMID 28779088, 2017). "Both CXCR4/SDF-1 and VLA-4/VCAM1 axes are involved in leukemia protection but little is known about the role of CCL2/CCR2 in AML biology and protection against chemotherapy." (PMID 28045930, 2017). "Expression of CXCR4 and CXCL12 was assessed by flow cytometry in primary leukemia cells from patients with CLL as well as in normal B, and stroma-NK-tert cells." (PMID 26646452, 2016). "We characterized the expression of CXCR4 in leukemia (CCRF-CEM) and lymphoma (Namalwa) cells by flow cytometry, and both cell lines expressed high levels of CXCR4." (PMID 26954567, 2016). "Collectively, these results suggest that like CXCR4/CXCL12, the CCR2/CCL2 and CCR5/CCL4 receptor/chemokine axes contribute to leukemia-MSC interactions, and that the chemokines expressed by MSCs are regulated, at least in part, by ARC in AML cells." (PMID 26956049, 2016). "We identify that, in addition to the well-known CXCR4/CXCL12 axis, CCR2/CCL2 and CCR5/CCL4 also drive leukemia/stromal interactions." (PMID 26956049, 2016). "AML biomarkers NPM1, FLT3, CXCR4, MMP9 and IGF-IR are also present in AML cell derived exosomes, along with mRNAs involved in leukemia development." (PMID 27191983, 2016). "We also selected miR-335 and miR-622, which are predicted to target uPAR- or CXCR4- 3′UTR and are expressed in HSC mobilization and/or leukaemia 41–43." (PMID 26082201, 2015). "In fact, uPAR and CXCR4 expression in AML varies according to the FAB subtype (highest expression in M5 and lowest in M0) 21,22,25, thus leukaemia cells seemed a suitable system to validate the expression and function of identified miRs." (PMID 26082201, 2015). "Among developed CXCR4 antagonists, peptides are one attractive kind to block CXCR4/CXCL12 axis and abrogate the stromal cell-mediated leukemia cell drug-resistance." (PMID 26538086, 2015). "Bone marrow represents the most important organ for the homing of leukemia cells, in which stromal cells secret CXCL12 for recruiting those expressing CXCR4." (PMID 25312253, 2014). "Taken into consideration limitations of the in vitro systems in the assessment of agents affecting tumor microenvironment, we evaluated the utility of combined blockade of CXCL12/CXCR4 and TGF-β signaling pathways in the in vivo leukemia model." (PMID 23826077, 2013). "Concordantly, the expression of surface proteins (CX3CR1, CXCR4, EMB, ITGB4, LSP, VCAM1) important for leukemia infiltration was downregulated in IGFBP2-null bone marrow AML cells." (PMID 24191913, 2013). "These factors include CXCR4/CXCL12 (SDF-1) signaling, which is involved in the homing, survival, and proliferation of leukemia cells in AML and chronic myeloid leukemia (CML)." (PMID 24304929, 2013). "Targeting CXCR4 effectively mobilizes AML cells to the peripheral blood, prevents extramedullary organ infiltration and metastasis, and exhibits significant anti-leukemia efficacy with minimal toxic side effects, suggesting its potential as a personalized therapeutic target for AML." (PMID 40427609, 2025). "Retrospective analyses incorporating CXCR4-directed ERT in chemotherapy-based conditioning before auto- or alloSCT in hematologic malignancies such as T- and B-cell lymphomas, multiple myeloma and leukemia have confirmed adequate engraftment 33, 38-40." (PMID 39744224, 2025).
leukemia (continued). "It is suggested that after Nrf2 overexpressed MSCs were co-cultured with Nalm-6/RS4; 11 cells, CXCR4 on Nalm-6/RS4; 11 cell surface can be an important factor activating the SDF-1/CXCR4 axis within the leukemia microenvironment, which further promotes Nrf2 overexpressed MSCs to react with ALL cells." (PMID 39081954, 2024). "Specifically, in leukemias, PTMA has been reported in fusion with OAZ1 and CXCR4." (PMID 38338888, 2024). "In leukemia, PFKP affected disease progression by influencing CXCR4-dependent T-cell infiltration." (PMID 38233508, 2024). "CXCR4-conjugated RBCEVs were loaded with the pro-apoptotic peptide KLA, demonstrating that these were able to significantly suppress leukemia burden and increase survival in a leukemia xenografted mouse model." (PMID 36839687, 2023). "Similarly, CXCR4 blocking also prevents leukemia-induced IL7 downregulation and inhibits leukemia growth." (PMID 36912771, 2023). "CXCR4 interacts with CXCL12 (CXC motif chemokine 12)/Stromal cell-derived factor-1 (SDF-1), that is a chemokine with a critical role for cells escaping from thymus to bone marrow, leukemia initiating cells and trans-endothelial migration." (PMID 36624522, 2023). "Similarly, exosomes rich in miR-150 can disrupt the CXCR4/CXCL12 axis; disruption of CXCR4/CXCL12 axis supports the leukemia growth." (PMID 35236376, 2022). "The leukemia cells of M5 patients with EMI appeared to have low expression of miR-3677-5p and high expression of the mRNA of CXCL12 and CXCR4, which may be used as indicators of EMI and poor prognosis." (PMID 36569343, 2022). "The leukemia cells in the EMI group showed abnormally low expression of miR-3677-5p but high expression of CXCL12 and CXCR4 mRNA, indicating that the miR-3677-5p/CXCL12 axis may be closely related to the occurrence of EMI in monocytic leukemia." (PMID 36569343, 2022). "Binding to CXCR4 with the β-hairpin mimicry, balixafortide inhibited the CXCL12-induced activation of downstream MAPK-ERK/PI3K-AKT pathways in the lymphoma and AML cell lines and blocked the CXCL12-dependent chemotaxis in breast cancer and leukemia cell lines." (PMID 36465350, 2022). "BMSCs can protect leukemia cells against chemotherapy drugs through various cytokines or growth factors (e.g., PDGF, VEGF, EGF, SCF, etc.)or cell-cell surface contact (e.g., SDF1/CXCR4, VLA4/VCAM1, CD44/E-selectin, etc.)." (PMID 34307365, 2021). "Understanding the function of the CD9 receptor in normal and malignant CD34+ and VSELs, along with its relationship with the CXCR4/SDF-1 pathway, will enable advances in the field of adult pluripotent cell usage in regenerative medicine and in their role in leukemia." (PMID 33918035, 2021). "Suggesting that the SDF-1/CXCR4 signal axis might be a significant factor in the process of MSCs with CAF-like phenotype promoting the migration and invasion of leukemia cells." (PMID 34733839, 2021). "Thus, the CXCR4/CXCL12 axis, regulated in part by a hyperactive Notch pathway, is involved in the homing and progression of several leukemia subtypes in the BM niche." (PMID 34394130, 2021). "Surprisingly, we do not find synergistic effect of CXCR4 inhibition with traditional chemotherapy in these leukemias, strongly suggesting caution in the broad use of these inhibitors, and a more tailored approach to this targeted therapy." (PMID 35070954, 2021). "We have therefore identified a subtype of leukemia that is not sensitive to anti-proliferative or cytotoxic effect CXCR4 inhibitors, despite high levels of CXCR4 expression and an intact CXCR4 signaling pathway." (PMID 35070954, 2021). "Deletion of Cxcr4 in AML cells eradicates leukemia cells in vivo without impairing their homing to the bone marrow." (PMID 32460032, 2020).
leukemia (continued). "CXCR4 blockade by LY2510924 inhibited the phosphorylation of ERK, which partially abrogated the stroma-mediated bypass of the FLT3 receptor, enhanced the apoptosis by quizartinib in co-culture conditions and facilitated anti-leukemia effects in vivo." (PMID 32629802, 2020). "However, the functional in vivo role of CXCR4 in AML has remained elusive; in particular, its role in homing of leukemia cells to the bone marrow, cell signaling, and interactions with CXCL12 is unclear." (PMID 32460032, 2020). "Compared with leukemia cells expressing normal Cxcr4 levels, Cxcr4 deletion did not affect MIF-induced growth or survival of leukemia cells." (PMID 32460032, 2020). "Apart from Cxcr4, the screen also identified Cd47 and Cd244 (also referred to as 2B4) as positive regulators of MLL-AF9 leukemia cells in vivo; both are known to play a role in immune regulation in normal hematopoiesis and to promote AML cell growth and survival." (PMID 32460032, 2020). "Consistent with our findings from the screen, GFP+ leukemia cells expressing Cxcr4 sgRNAs transplanted into sublethally irradiated recipient mice showed strong depletion in the bone marrow and spleen compared with GFP+ leukemia cells expressing a control sgRNA." (PMID 32460032, 2020). "To further assess whether CXCR4 is essential for full leukemia development in vivo, we sorted GFP+ (sgRNA-expressing) leukemia cells and transplanted them into sublethally irradiated mice." (PMID 32460032, 2020). "In contrast, a corresponding competition assay in vitro with standard cytokines (interleukin-3 [IL-3], IL-6, and stem cell factor [SCF]) demonstrated that disruption of Cxcr4 in c-Kit+ leukemia cells did not affect cell proliferation." (PMID 32460032, 2020). "CXCR4 together with CXCL12 is important for the interaction of leukemic stem cells (LSCs) with the microenvironment by promoting quiescence and inhibiting apoptosis in LSCs and therefore inducing therapeutic resistance in leukemia." (PMID 32456310, 2020). "CXCR4 and chemotaxis genes in DUX4-translocated leukemia may contribute and enhance leukemia-stroma interactions facilitating DUX4 blasts to survive treatment." (PMID 30862934, 2019). "To characterize the effects of PF-06747143 on leukemia progression, we used two different patient-derived xenograft (PDX) models: Patient 17CXCR4-low and P15CXCR4-high models, characterized by relatively low and high CXCR4 expression, respectively." (PMID 28779088, 2017). "New approaches to overriding stromal cell-associated chemoresistance, such as the use of agents that inhibit the CXCR4-SDF-1 axis, could potentially improve leukemia patient response and survival if developed as anticancer therapeutics." (PMID 29299123, 2017). "Eμ-Tcl1 Tg leukemias exhibited heterogeneous surface staining for CXCR4, CXCR5 and CCR7, but were negative for CXCR3." (PMID 27843137, 2017). "It is shown that CXCR4, a receptor for CXC chemokine receptor 12 (CXCL12), is a central player in migration and homing to tissue niches of leukemia cell that support cell survival, growth and drug resistance; and has proved to be an adverse prognostic indicator of AML." (PMID 27706258, 2016). "In fact, CXCR4 inhibition by LY2510924, a selective and small peptide CXCR4 antagonist without any effector function also induced apoptosis in vivo in the same leukemia CEM model (unpublished observations)." (PMID 26954567, 2016). "Bone marrow stroma can protect acute myeloid leukemia (AML) cells against chemotherapeutic agents and provide anti-apoptosis and chemoresistance signals through secreting chemokine CXCL12 to activate its receptor CXCR4 on AML cells, resulting in minimal residual leukemia and relapse." (PMID 26538086, 2015). "Given the reduced importance of CXCR4/CXCL12 in CML compared with normal HSCs, and CXCR4 antagonists are potential therapeutics for treatment of CML, the particular application that captures our attention is the recurrence of active leukemia." (PMID 27429863, 2015).
leukemia (continued). "Third, understand how the CXCR4/CXCL12 axis is involved in tumor functions, such as how LSC homing and signaling transduction helped translate findings into additional clinical uses in leukemia and solid tumors." (PMID 27429863, 2015). "In summary, our data demonstrate that plerixafor is an effective inhibitor of CXCR4 in pediatric ALL and that the timing of administration may be critical to optimizing its use as a chemosensitizing agent in leukemia." (PMID 25333254, 2014). "Another attractive feature of E5 is that it neither induces nonmalignant cell apoptosis at a high concentration of 80 μM nor activates CXCR4 signal pathway of the leukemia cells." (PMID 25312253, 2014). "CXCR4 and its ligand, SDF-1, are important regulators of stromal/leukemia cell interactions." (PMID 25295230, 2014). "Presence of functional circulating CXCR4 bearing microparticles was correlated with high white blood count in AML patients and was proposed to be involved in AML progression, possibly by promoting dissemination of leukemia." (PMID 22346731, 2012). "Many known HIF-1α targets could mediate the protection conferred by hypoxia, and a number of those have been validated as chemoresistance factors in leukemias (i.e., MDR-1, Nur-77, CXCR4 and others)." (PMID 21853076, 2011). "This approach, first validated in transfected cells by detecting the presence of CXCR4 and ACKR3 homo-oligomers and hetero-oligomers, reveals for the first time endogenous CXCR4 homo-oligomers in non-transfected human leukemia/lymphoma-derived cancer cell lines." (PMID 41402431, 2025). "However, it remains unclear whether SDF-1/CXCR4 axis mediates the interaction between Nrf2 overexpression in MSCs of B-ALL and leukemia cells." (PMID 39081954, 2024). "In summary, various studies suggest that CXCR4 inhibition may be beneficial for the treatment of ALL, yet further research is required to fully understand the comprehensive effects of targeting the leukemia microenvironment." (PMID 38920657, 2024). "While CXCR4 expression and signaling may be a contributing factor to extramedullary disease, its impact appears limited to initial release and migration of leukemia cells from the marrow and is not specific to MS development." (PMID 36900239, 2023). "Taken together, the current research status is not sufficient to answer the question whether FLT3 and CXCR4 act together or independently in leukemia progression." (PMID 37849810, 2023). "have demonstrated that the combination of the CXCR4 antagonist LY2510924 and the FLT3 inhibitor quizartinib reversed the stroma-mediated resistance against the FLT3 inhibitor and induced the mobilization and differentiation of AML cells in mice, resulting in enhanced anti-leukemia effects." (PMID 37849810, 2023). "Interestingly, these chemokines, abundant in leukemia-conditioned MSC supernatants, were able to potently attract B-ALL cells that, besides CXCR4, showed high membrane levels of CCR4 (CCL22 and CCL2 receptor) and variable levels of CXCR1/2 (CXCL1 and CXCL8 receptors)." (PMID 33922612, 2021). "Immunotherapies may be more suitable in combination with CXCR4 antagonists because they are not affected by drug‐resistant leukaemia cells." (PMID 34050566, 2021). "However, whether the SDF-1/CXCR4 axis mediates the interaction between MSCs with CAF-like phenotype and leukemia cells in B-ALL is unclear." (PMID 34733839, 2021). "As Src kinase family was described as a player in CXCL12/CXCR4 and PI3K or MAPK pathway in severe solid tumor, we hypothesized whether HCK could be a downstream target of CXCL12/CXCR4 pathway and contribute to the pathophysiology of leukemia cells." (PMID 33842460, 2021). "However, new evidence emerged that drug‐resistant leukaemia cells were not affected by CXCR4 antagonists, and the migration of certain leukaemia cells to the leukaemia niche was independent of SDF‐1/CXCR4 axis." (PMID 34050566, 2021).